LAMP5 (lysosome associated membrane protein 5)
Description:
Plays a role in short-term synaptic plasticity in a subset of GABAergic neurons in the brain.
Synonyms: BAD-LAMP; LAMP-5; C20orf103; dJ1119D9.3; UNC-46; BADLAMP
Tractability: Antibody: UniProt places it where antibodies can reach, with high confidence; its Gene Ontology location is reachable by antibodies, with high confidence; UniProt predicts a signal peptide or a membrane-spanning region.
Gene: Protein-coding gene on chromosome 20 (9,514,316 to 9,530,541, forward strand). Ensembl gene ENSG00000125869.
Subcellular location: Cell membrane; Cytoplasmic vesicle, secretory vesicle, synaptic vesicle membrane; Endoplasmic reticulum-Golgi intermediate compartment membrane; Endosome membrane; Cytoplasmic vesicle membrane; Cell projection, dendrite; Cell projection, growth cone membrane; Early endosome membrane; Recycling endosome
Subcellular location (Human Protein Atlas): Cytosol; Centriolar satellite; Mitotic spindle
Gene Ontology:
Biological process: establishment of protein localization to organelle; presynaptic modulation of chemical synaptic transmission
Cellular component: endoplasmic reticulum-Golgi intermediate compartment membrane; endosome membrane; plasma membrane; cytoplasmic vesicle membrane; dendrite membrane; early endosome membrane; growth cone membrane; late endosome membrane; lysosomal membrane; recycling endosome; recycling endosome membrane; dendrite; GABA-ergic synapse; late endosome; lysosome; membrane; synaptic vesicle; synaptic vesicle membrane
Genetic constraint (gnomAD): Loss-of-function variants: 36 observed, 29.95 expected, observed/expected ratio (o/e) 1.2, 90% interval 0.92 to 1.59. The upper end of that interval is the gene's LOEUF score, 1.59, which puts it in group 6 of 6, group 1 being the genes least tolerant of losing a copy. Missense variants: 377 observed, 359.26 expected, observed/expected ratio (o/e) 1.05, 90% interval 0.96 to 1.14. Synonymous variants: 149 observed, 138.25 expected, observed/expected ratio (o/e) 1.08, 90% interval 0.94 to 1.24.
Homologues: Orthologues: chimpanzee LAMP5 (99% identical), macaque LAMP5 (98% identical), dog LAMP5 (94% identical), pig LAMP5 (94% identical), guinea pig LAMP5 (93% identical), rat Lamp5 (91% identical), rabbit LAMP5 (89% identical), mouse Lamp5 (86% identical), tropical clawed frog lamp5 (61% identical), zebrafish LAMP5 (40% identical), Drosophila melanogaster CG32225 (21% identical). Paralogues in human: LAMP1 (21% identical), CD68 (18% identical), LAMP2 (16% identical).
Diseases named in the same sentence as LAMP5 in open-access papers:
LAMP5 is named in the same sentence as 32 diseases in open-access papers, as found by Europe PMC text mining. Sharing a sentence is not in itself a finding about the gene and the disease. The quoted sentences say what the papers report.
gastric cancer (8 papers, 2017 to 2025). A primary or metastatic malignant neoplasm involving the stomach. "In gastric cancer, the upregulation of LAMP5 in metastatic tissues is associated with enhanced cell proliferation, invasion, migration, and alterations in apoptosis and the cell cycle, indicating its significant role in metastasis formation and potential as a drug development target." (PMID 38515748, 2024). "LAMP5, a lysosome-associated membrane protein, plays a crucial role in leukemia and gastric cancer." (PMID 38515748, 2024). "Lysosomal-associated membrane protein LAMP5 is involved in gastric cancer and leukemia." (PMID 36835984, 2023). "In gastric cancer, LAMP5 was upregulated in metastatic tissues, and LAMP5 knockdown significantly inhibited gastric cancer cell proliferation, invasion and migration, and increased apoptosis, cell cycle arrest and cancer stemness." (PMID 37033323, 2023). "Recent publications have also proposed the role of some other genes found as prognostic markers, like the case of LAMP5 that has been included in a multigenic assay to predict recurrence for gastric cancer patients after surgery." (PMID 30537927, 2018). "LAMP-5 is a prognostic biomarker in both gastric cancer and CRC." (PMID 40277899, 2025). "Moreover, LAMP-5 promotes metastatic potential, as high LAMP-5 mRNA levels are significantly associated with a worse prognosis in gastric cancer cells." (PMID 40277899, 2025). "Previous studies had shown that LAMP5 could serve as a prognostic signature to predict survival in patients with gastric cancer, and its high expression levels could accurately estimate KMT2A-r in acute leukemias." (PMID 37701829, 2023). "Contrary to the results of this study, increased expression of four genes (CLIP4, NOX4, LAMP5, and MATN3) is related to poor prognosis, and the expression of these genes is higher in stromal components than in epithelial cancer cells in gastric cancer." (PMID 33575272, 2020). "Thus, in metastatic tissues, LAMP-5 expression is increased, while knocking out LAMP-5 significantly inhibits the proliferation, invasion, and migration of gastric cancer cells by promoting apoptosis, cell cycle arrest, and cancer stemness." (PMID 40277899, 2025).
leukemia (7 papers, 2020 to 2024). A malignant (clonal) hematologic disorder, involving hematopoietic stem cells and characterized by the presence of primitive or atypical myeloid or lymphoid cells in the bone marrow and the blood. "miR-543 interacts with LAMP5 (lysosome-associated membrane protein), very recently shown to be an autophagy suppressor that protects leukemia fusion oncoproteins, helping these to evade degradation." (PMID 32605588, 2020). "As a consequence, several studies identified LAMP5 overexpression in KMT2A-r leukemia." (PMID 35734412, 2022). "Because KMT2A is a promiscuous gene and the distribution of fusion partners varies according to leukemia subtypes, we hypothesized that SKIDA1 and LAMP5 expression could be associated with specific gene rearrangements." (PMID 35734412, 2022). "LAMP5, a lysosomal associated membrane protein, could directly target the oncogenic MLL-fusion protein, whose depletion lead to inhibition in leukemia cell growth in vivo and in vitro." (PMID 34566519, 2021). "LAMP5 is specifically and highly expressed in MLLr leukemia." (PMID 32456310, 2020). "In leukemia, particularly mixed-lineage leukemia rearrangements (MLL-r), LAMP5 is a direct target of the oncogenic MLL fusion protein, and its reduction significantly inhibits leukemia cell growth, highlighting its potential as a therapeutic target." (PMID 38515748, 2024). "Considering each subtype of leukemia, the most divergent performance was observed in T-ALL, in which SKIDA1 had the best estimates (AUC: 0.991; CI: 0.981–1.000), followed by LAMP5 (AUC: 0.716; CI: 0.570–0.861), and CSPG4 (AUC: 0.558; CI: 0.418–0.698)." (PMID 35734412, 2022). "As a highlight, LAMP5 expression was able to predict even the rare gene fusion KMT2A-USP2, which is often missed by routine methods, and that gene product also appears to be a potential treatment target in KMT2A-r leukemia." (PMID 35734412, 2022). "Thus, LAMP5 may serve as both a marker and treatment target in KMT2A-r leukemia." (PMID 35734412, 2022).
Alzheimer disease (5 papers, 2022 to 2024). A progressive, neurodegenerative disease characterized by loss of function and death of nerve cells in several areas of the brain leading to loss of cognitive function such as memory and language. "The EC is one of the first regions of the brain to be affected in Alzheimer’s disease, and previous work has linked cognitive decline to the loss of LAMP5+RELN+ cells." (PMID 38122823, 2024). "LAMP5 expression in mice is confined to neurons, and LAMP5 interneuron deletion causes neural network dysfunction in Alzheimer’s disease." (PMID 37033323, 2023). "Recent studies have identified the loss of Lamp5 (novel regulator of neuronal hyperexcitation critical for survival of distinct interneuronal populations) in Alzheimer's disease, resulting in dysfunction of cortical networks that are linked to cortical hyperexcitability and neurodegeneration." (PMID 38504632, 2024).
Anxiety (4 papers, 2016 to 2020). Intense feelings of nervousness, tension, or panic often arise in response to interpersonal stresses. "In conclusion, LAMP5-deficient mice showed normal activity and motor behavior but had decreased anxiety levels." (PMID 27272053, 2016). "In our study, we found that Lamp5 shows lower expression in proestrus than in dioestrus females, which is consistent with lower anxiety levels in proestrus compared to dioestrus and with the behavioural phenotype of the Lamp5−/− mice." (PMID 31253786, 2019). "At the behavioral level, LAMP5 mutant mice showed decreased anxiety and deficits in olfactory discrimination." (PMID 27272053, 2016). "Consistent with such a critical function in fine-tuning specific GABAergic synapses, LAMP5 KO mice show subtle behavioral abnormalities, as evidenced by decreased anxiety and altered odor discrimination." (PMID 27272053, 2016). "Open field, elevated plus maze and rotarod tests showed that Lamp5 KO mice have no overt abnormalities in locomotor activity, anxiety-related behavior, motor coordination and motor learning." (PMID 30867010, 2019).
acute leukemia (3 papers, 2022 to 2023). A clonal (malignant) hematopoietic disorder with an acute onset, affecting the bone marrow and the peripheral blood. "LAMP5, a member of lysosome-associated membrane protein family, was upregulated in various kinds of tumor, such as colon adenocarcinoma and acute leukemia." (PMID 35655081, 2022). "SKIDA1 expression may predict those rearrangements in most subtypes of acute leukemia, while LAMP5 presents good performance to point out KMT2A-r in B-ALL and ALAL, including the KMT2A-USP2 fusion." (PMID 35734412, 2022). "Therefore, we were able to point out biomarkers (e.g., SKIDA1 and LAMP5) to predict KMT2A-r regardless of acute leukemia subtypes." (PMID 35734412, 2022). "The SKIDA1 (AUC: 0.839; CI: 0.799–0.879) and LAMP5 (AUC: 0.746; CI: 0.685–0.806) overexpression were the better markers associated with KMT2A-r compared to CSPG4 (also named NG2; AUC: 0.722; CI: 0.659–0.784), regardless of the type of acute leukemia." (PMID 35734412, 2022).
dementia (3 papers, 2022 to 2025). Loss of intellectual abilities interfering with an individual's social and occupational functions. "However, when analyzing ncRNAs, we identified a distinct enrichment pattern of these diseases in different cell types, and certain disorders were exclusively linked to ncRNAs, such as dementia with Lamp5, ASD with Sncg, ADHD with Sst and Pvalb, and MDD with L2/3 IT PPP and L6 IT ENTI." (PMID 38660385, 2024).
multiple myeloma (3 papers, 2022 to 2025). "As LAMP5 was overexpressed in LCE-multiple myeloma, we hypothesized that this cell subpopulation may have been prone to cause lytic bone disease in our patient." (PMID 39699274, 2025). "LAMP5 was the specifically overexpressed just in LCE-multiple myeloma." (PMID 39699274, 2025). "MYC has long been appreciated as an important oncogene in multiple myeloma, whereas scRNA-seq studies have implicated LAMP5 to be a novel overexpressed gene in multiple myeloma." (PMID 39699274, 2025). "Interestingly, localized LAMP5 overexpression has been reported in osteolytic lesions, one of the most debilitating complications of multiple myeloma." (PMID 39699274, 2025). "We first found that Lysosome associated membrane protein 5 (LAMP5) expression was sequentially increased in healthy donors (HD), monoclonal gammopathy of undetermined significance (MGUS), smoldering multiple myeloma (SMM) and newly diagnosed MM (NDMM), relapsed MM (RMM)." (PMID 37033323, 2023). "Interestingly, LAMP5 has also been found to be upregulated in active multiple myeloma compared with smoldering multiple myeloma and thus may contribute directly to symptomatic myeloma diagnosis through development of bone lesions." (PMID 39699274, 2025). "To evaluate the generalizability of the link between LAMP5 and osteolysis in patients with multiple myeloma, we compared the LCE-multiple myeloma gene signature in larger cohorts of patients." (PMID 39699274, 2025). "Next, we evaluated whether LAMP5 and the other most overexpressed genes in the subclonal LCE-multiple myeloma subpopulation affected prognosis on their own." (PMID 39699274, 2025). "Thus, the times in which the LAMP5-high subpopulation was prevalent corresponded to calcium spikes, implying a direct link between the features of LCE-multiple myeloma and osteolysis." (PMID 39699274, 2025). "Whereas the IGH-multiple myeloma gene signature was most notable for elevated IGH, the LCE-multiple myeloma signature contained biologically intriguing transcript elevations including LAMP5 and MYC." (PMID 39699274, 2025). "Our findings connecting LAMP5 to the development of OL is supported by a recent retrospective trial in which bulk GEP was performed on PC from patients with smoldering myeloma with and without progression during follow-up." (PMID 35145077, 2022). "Interestingly, we found that LAMP5 knockdown did not affect myeloma cell viability or induce apoptosis in cell lines." (PMID 39699274, 2025).
catalepsy (1 paper, 2016). A nervous system disorder characterized by diminished responsiveness and consciousness, and rigidity of the body. "In this context, LAMP5-deficiency is expected to reduce haloperidol-induced catalepsy." (PMID 27272053, 2016).
epilepsy (1 paper, 2020). A brain disorder characterized by episodes of abnormally increased neuronal discharge resulting in transient episodes of sensory or motor neurological dysfunction, or psychic dysfunction. "Finally, the Light Green Cluster highlighted the selective effect of epilepsy on upper-layer L2–3_Cux2_Lamp5 and L2–3_Cux2_Frem3 principal neurons that consist of dysregulated neuronal morphogenesis GO terms." (PMID 33028830, 2020).
cancer (8 papers, 2021 to 2025). A tumor composed of atypical neoplastic, often pleomorphic cells that invade other tissues. "Although less studied compared to LAMP1 and LAMP2, LAMP5 overexpression is associated with lysosome repositioning to the cell periphery in mixed lineage leukemia, and the promotion of cancer stemness and EMT in gastric cancer." (PMID 38474423, 2024). "Additionally, an association between LAMP-5 and cancer progression through autophagy and macrophage invasion has also been reported." (PMID 40277899, 2025). "An increased expression of the LAMP-family protein LAMP5, as well as the lysosomal integral protein LIMP2, has also been associated with cancer progression and metastasis in various cancers." (PMID 38474423, 2024). "Within distinct neoplastic entities, modulations of LAMP5's lysosomal operation bear the potential to affect cancer cellular dynamics." (PMID 37314494, 2023). "While previous LAMP5 studies mainly focus on its role in cancer, insights into its function in the brain remain limited, despite its brain-specific expression pattern." (PMID 35780436, 2022). "Elevated LAMP-5 has been reported in various types of cancer." (PMID 40277899, 2025). "Among them, LAMP1, LAMP2, LAMP4 and LAMP5 have been studied in relation to cancer and immunity." (PMID 38146591, 2024).
tumor (5 papers, 2020 to 2025). "Some studies proved that the dysregulation of LAMP5 was related to the infiltration of tumor immune cells and associated with the poorer prognosis of COAD patients." (PMID 35655081, 2022). "Additionally, extracellular matrix cancer-associated fibroblasts (emCAFs_LAMP5) interact with endothelial cells and thyrocytes, promoting tumor angiogenesis and metastasis more prominently in CAYA patients." (PMID 40719066, 2025). "Based on these findings, we suggest that LAMP5 is a key gene in the occurrence of MM and plays a tumor-promoting role in MM, with a mechanism of action exerted in part through activation of the P38 protein." (PMID 37033323, 2023). "The GSE54129 GC dataset and LASSO regression model (tumor vs. normal) were employed, and 6 significant differentially expressed genes (LAMP5, CEBPB, ARMC9, PAOX, VMP1, POC1A) were identified." (PMID 33052878, 2020). "Mechanistically, LAMP5 may exert its pro-tumor effects in MM in part through activation of p38 protein." (PMID 37033323, 2023). "We screened LAMP5 for the first time as a key gene for MM progression and recurrence, and found that LAMP5 may exert its pro-tumor effects in MM through activation of p38 protein." (PMID 37033323, 2023). "SPINK1, FABP4, and MMP10 showed darker staining in tumor tissues, and GPRASP1, CLCA4, and LAMP5 showed lighter staining." (PMID 35479956, 2022).
neurological disease (1 paper, 2024). "Assessing for the dysfunction of Lamp5 and related modulators of cortical inhibitory interneuronal function, with a view to unlocking the initial pathogenic event in ALS, may further inform pathophysiological insights into neurological disease and lead to development of novel therapeutic strategies." (PMID 38504632, 2024).
LAMP5 also shares sentences with these, for which no sentence is quoted: amyloid (1 paper); Astrocytoma (1); breast carcinoma (1); cognitive decline (1); colon adenocarcinoma (1); colon cancer (1); COVID-19 (1); depression (1); epilepsy syndrome (1); focal epilepsy (1); Frontotemporal lobar degeneration (1); lung carcinoma (1); meningioma (1); monoclonal gammopathy of undetermined significance (1); neurodegenerative disease (1); oligoastrocytoma (1); oligodendroglioma (1); pancreatic cancer (1); temporal lobe epilepsy (1); viral infections (1).